APC (APC regulator of Wnt signaling pathway)
Diseases named in the same sentence as APC in open-access papers (continued):
Sharing a sentence is not in itself a finding about the gene and the disease.
tumor (continued). "Compared to adjacent non-tumor tissues, HCC specimens exhibited increased β-catenin and decreased APC expression." (PMID 41493695, 2026). "By contrast, Ptennull-primed tumours exhibited a notable distal shift from BB combinations that resulted in retention of the entire Armadillo repeat domain while still generating loss of the 20 amino acids present in bin E. Armadillo repeat domains mediate APC’s role in cell–cell adhesion." (PMID 41339549, 2026). "FMRP interacts with both GSK3β and CTNNB1, MSI1 represses APC and enhances Wnt signaling in epithelial progenitors, while MEX3A stabilizes LGR5 and represses DKK1, thereby promoting stemness and tumor progression." (PMID 41516083, 2025). "DSS-treated APC mut and APC; KRAS mut mice exhibited widespread tumor formation throughout the colon, predominantly in the distal region." (PMID 41285904, 2025). "In contrast, all 11 tumors from APC; KRAS mut mice were classified as Branched Type Tumor (P < 0.01)." (PMID 41285904, 2025). "TSGs such as RASSF1, APC, CDKN1A, CDH1, NEFH34, and NOTCH3 regulate various molecular pathways involved in metastasis and tumor progression." (PMID 41011154, 2025). "A similar pattern was observed in APC; KRAS mut mice treated with DSS, which exhibited widespread tumor formation throughout the colon." (PMID 41285904, 2025). "Conversely, tumor-suppressive circRNAs such as circ-CTNNB1 inhibit Wnt signaling by sequestering miR-520h, which targets APC, which is a key negative regulator of β-catenin." (PMID 40649179, 2025). "Although clinical translation is still in early stages, these strategies offer the potential to selectively target APC-mutant CRC and mitigate Wnt-driven tumor progression." (PMID 41228231, 2025). "Since this seminal discovery, mutations in genes that encode components of Wnt signaling, including adenomatous polyposis coli (APC), β-catenin (CTNNB1), and Axin, as well as several Wnt target genes, have been identified in a variety of tumor types." (PMID 41218118, 2025). "Co‐occurring alterations with KRAS included FLT1 (28%, 9/32, p = 0.033), APC (16%, 5/32, p = 0.015), and KEAP1 (16%, 5/32), with four of these tumours also harbouring STK11 alterations, forming a KRAS‐KEAP1‐STK11 mutational profile (13%, 4/32)." (PMID 41015991, 2025). "We also detected the enrichment of proteins interacting with the ubiquitination pathway (e.g. tumour suppressors SMAD2, APC, and AXIN1)." (PMID 39660592, 2024). "APC regulates the expression of β-catenin, a major component of the WNT signaling pathway, and suppresses tumor progression." (PMID 38356709, 2024). "Based on these findings, 11 pairs of tumor and adjacent tissues before RFA and after RFA were collected for assessing mRNA expression of APC, FAS, HGF, PCNA and EFCAB7." (PMID 39276379, 2024).
tumor (continued). "Reduced APC expression unleashes the suppression of MYC and PKM2, thereby leading to enhanced aerobic glycolysis, tumor cell proliferation and tumor formation." (PMID 37192910, 2023). "In the 11 patients whose cancer developed in a background of histologically normal-appearing non-neoplastic mucosa, we found a higher frequency of APC mutations, suggesting that some of these may represent cancers that did not develop as a result of inflammation-induced neoplasia." (PMID 36611031, 2023). "Central to this pathway is the so-called destruction complex, a multifactorial assembly comprising among others the tumor suppressors AXIN and APC, CASEIN KINASE1α (CK1α), and GLYCOGEN SYNTHASE KINASE 3 (GSK3)." (PMID 36609428, 2023). "The most investigated genes were RASSF1A, BRCA1, OPCML, APC, HIC1, and HOXA9, all being tumor-suppressor genes." (PMID 36788585, 2023). "To research the function of HOXB3 activation in APC-suppressed tumors (one type of WNT-ON tumor), we introduced a doxycycline-inducible shRNA targeting HOXB3 (Tet-off) into the LNCaP-AI cells with APC knockdown (LAPCi-HOXB3Tet for short)." (PMID 36973255, 2023). "In the APC/SMAD4 mutant mouse model of CRC, the expression of CCL9 was found to be upregulated in the tumor epithelium and knockout of CCR1 prevented immature myeloid cell (also known as myeloid derived suppressor cells or MDSCs) accumulation at the tumor." (PMID 36982211, 2023). "To assess the correlation of APC expression levels to the prominent drug efflux transporters, MDR1 and MRP1, we used the patients’ tumor protein lysates and measured the protein levels of APC, MDR1, and MRP1." (PMID 37108784, 2023). "Here, our findings showed APC, TCF, WNT, AXIN, and CTNNB1 genes were overexpressed in tumor tissues in comparison to the adjacent normal tissues." (PMID 37644520, 2023). "In contrast to the data distribution of the APC gene before SMOTE sampling, the original data distribution of sequences from the ATM gene were relatively balanced as the tumor sequences comprised of 53% of the total data, and normal DNA sequences made up 47%." (PMID 36959534, 2023). "APC is a multi-functional tumor suppressor gene that suppresses the canonical Wnt pathway via forming the complex with AXIN and GSK3, where the APC-AXIN-GSK3 complex inhibits Wnt signaling via promoting β-catenin ubiquitination." (PMID 37671945, 2023).
tumor (continued). "The results showed that BCL2, APC, TCF, WNT, AXIN, and CTNNB1 (p < 0.05) were significantly higher expressed in tumor tissues compared to adjacent healthy tissues, and BAX was higher in control tissues than tumor tissues (p < 0.05)." (PMID 37644520, 2023). "Interestingly, in ML10 CDH1WT where the DCIS was profiled, promoter methylation of WNT pathway genes were detected in the Abr component, including APC and CTNNA2 and may reflect the earlier divergence and underlying drivers of abrogated cell–cell adhesion in this tumour." (PMID 35053458, 2022). "The expression levels of BAX (p = 0.0017), ERH (p = 0.0067), APC (p = 0.0416), and CNBP (p = 0.0244) were significantly higher in tumor tissues of the NBL group than in the control group." (PMID 35991559, 2022). "A study showed that clofarabine inhibited the proliferation of tumor cells by downregulating DNMT1 and inhibiting the methylation of TSG, such as PTEN, APC, and RARβ2." (PMID 37077808, 2022). "Generally, tumor suppressor genes such as BRCA1, RB, and APC lose function through deletions or truncating variations in cancer cells." (PMID 36045334, 2022). "Mechanistically, epithelial TGFβ signalling induces a growth-promoting EGFR-signalling module that synergises with mutant APC and KRAS to drive MAPK signalling that re-sensitise tumour cells to MEK and/or EGFR inhibitors." (PMID 36477656, 2022). "However, other members of the WNT signaling pathway like the tumor suppressor genes APC, Axin1, or Axin2/Conductin were shown to harbor mutations as alternative genetic alterations, while only CTNNB1 and APC mutations were found in a substantial fraction of WNT-MBs." (PMID 36181537, 2022). "Given APC is mutated in up to 80% of CRC27, we sought to determine whether constitutive activation of epithelial TGFβ/ALK5 receptor signalling would promote or suppress tumour development induced by Apc loss and whether such pathway crosstalk could be recapitulated in organoids." (PMID 36477656, 2022). "For example, an APC-knockout CRC mouse model revealed that restoration of APC function promoted cell differentiation and sustained tumor regression." (PMID 33919924, 2021). "In line with this, NAC treatment reduced tumor formation and extended the survival of APCfl/fl Lgr5GFP-CREER RAC1fl/fl mice in which APC was conditionally deleted in crypt stem cells upon tamoxifen treatment." (PMID 33557356, 2021).
tumor (continued). "Moreover, the stress condition induced increased protein expression of β-Catenin and APC in primary tumor-derived cells both with or without APC mutation; in particular, APC showed a decrease in its full-length isoform and an increase in its stress-sensitive short isoform." (PMID 34885156, 2021). "When APC was overexpressed in SW116 cells with high KRT17 expression, tumor cell invasion and metastasis were inhibited to a certain extent, while the expression of β-catenin was significantly lowered." (PMID 34935584, 2021). "As a result, unlike NEDD4-1 or WWP2, FBXO22 did not affect AKT activation, but negatively regulated nuclear PTEN functions, such as the activity of APC/C-CDH1 complex and alternative splicing, to play a tumor-promoting role." (PMID 32249768, 2020). "Further, the gene expression profiling of the tumour exhibited a higher level of EPCAM, CK20, KRAS, AKT1, BRAF and CD133 expression, while lower levels of expression were observed in NANOG, MMP9 and APC genes." (PMID 33092235, 2020). "Thus, initial inactivating APC events in the colon might lead to an autocatalytic type reaction, epistasis, and genetic instability that might explain early tumor expansion and emergence of various tumor subclones as described in the big bang model of CRC development." (PMID 32079164, 2020). "Our finding of an increased proportion of APC mutations occurring outside the MCR in EOCRC suggests that the β-catenin binding capacity of truncated APC is of less importance in EOCRC than in older patients, and that alternative functions of APC may be at play in these tumours." (PMID 33352971, 2020). "It was recently shown that APC regulated the expression of the mitochondrial pyruvate carrier (MPC), affecting pyruvate metabolism and promoting tumor development." (PMID 33105836, 2020). "Our data provides further clues for both the similarity (regarding PTEN) and difference (regarding APC) between UrC and CRC and suggest that these tumor types are similar yet distinct on the molecular level." (PMID 32754865, 2020). "Pathway analysis showed activation of the transforming growth factor-β pathway in YSTs, which is associated with the overexpression of GATA6 and FOXA2 and the hypermethylation of tumor-suppressor genes (e.g., RASSF1, RUNX3, HIC1, or APC)." (PMID 32999426, 2020). "MLH1, APC, PTEN, P16, and CDX1/2 are bona fide TSGs whose promoter hypermethylation and tumor-suppressing functions in CRC have been experimentally verified." (PMID 32678024, 2020). "In gain-of-function experiments, ectopic expression of circ-APC inhibited DLBCL cell proliferation in vitro and tumor growth in vivo." (PMID 31631067, 2019). "As mentioned, the C-terminus of APC is frequently lost in CRC, indicating that it is essential for the APC tumor suppressive role." (PMID 31614493, 2019).
tumor (continued). "As APC negatively regulates the canonical WNT pathway, it is likely that it can act as a tumor suppressor." (PMID 31382613, 2019). "UHRF1 is also associated with epigenetic silencing of various tumor suppressors and other tumor-related genes, including CDKN2A, RB, BRCA1, RASSF1, PPARG, APC, CDH1, and RGS2." (PMID 31064417, 2019). "However, the lack of both pAKT and PTEN staining in the Apc2+/+ tumour may result from the hypomorphic APC allele on its own being an insufficiently strong driver of WNT signalling to activate PI3K/AKT signalling via established cross-talk mechanisms." (PMID 31291912, 2019). "Promoter regions of tumor suppressor genes hMLH1, MGMT, APC, and CDH1 were found to be hypermethylated in early stages of tumor formation in colon adenocarcinomas." (PMID 31244652, 2019). "They observed the APC, AXIN2, DKK3, SFRP2, 4, 5, WIF1, and WNT5a promoter methylation in 35.2, 32.8, 40, 46.4, 28.8, 26.4, 41.6, 22.4% of tumor samples, respectively." (PMID 30579343, 2018). "Therefore, Wnt inhibition may prevent tumours developing from more serrated routes, which are often associated with a lack of APC mutation and carry BRAF or KRAS mutations." (PMID 29556067, 2018). "For the small intestine tumor model, independently from the CX3CR1 status, APC+/min and WT mice were shaved and injected, 24 h before the acquisition, with 0.08 nmol/g of body weight of IntegriSense750 probe after 14 and 18 weeks of age." (PMID 30140377, 2018). "Wnt signalling probably facilitates the phosphorylation of CTNNB1 and APC by GSK3B and is likely to function as a tumor suppressor." (PMID 30447692, 2018). "The average tumor area was significantly reduced in CDX2;APC;PID mice (3 mm2) compared with those found in CDX2;APC mice (14 mm2)." (PMID 30150766, 2018). "As the important tumor suppressor genes, RASSF1A and APC were found to involve into cellular adhesion, apoptosis and cell cycle arrest." (PMID 28938637, 2017). "In CRC, many E3 ligases, including APC, RNF43, and FBW7, have been reported to act as tumor suppressors." (PMID 29296225, 2017). "The tumor tissues from each group were collected and the Q-PCR results showed that all the siRNA-DNMT1 and 5-Aza-CR enhanced the expression of RASSF1A and APC by demethylation." (PMID 28938637, 2017). "Four of these genes (ARID1A, APC, CDKN2A, and ID3) showed significantly reduced protein expression in the majority of tumor samples, whereas the remaining four genes displayed changes only in a few tumors." (PMID 29109526, 2017). "In contrast, drugs that affect the Wnt pathway upstream of APC truncation have not been tested for use in cancers harboring APC mutations, even though one of these agents, Secreted Frizzled-Related Protein 1 (sFRP1), was found effective in preclinical tumor models." (PMID 28708837, 2017). "A potential correlation between the site of APC truncation and TNKSi sensitivity has been explored, both in CRC cell lines and tumour‐derived cells from patients." (PMID 28910490, 2017). "Methylation levels ≥ 25% were only obtained for the promoters of APC in 44% (8/18), BRCA1 and CDKN2A in 11% (2/18) and ESR2 in 12% (2/17) of the tumor tissues and in addition for ESR2 in 6% (1/18) of the tumor-distant tissues." (PMID 28403857, 2017). "Thus, the mutation frequency of APC in the present study fell within the range reported in Asian populations but was lower than that in European or US populations, pointing to the potential role of an IDO1-regulated molecular pathway in tumor formation in Asian populations." (PMID 27578919, 2016).